FABP2 (fatty acid binding protein 2)
Diseases named in the same sentence as FABP2 in open-access papers (continued):
Sharing a sentence is not in itself a finding about the gene and the disease.
COVID-19 (17 papers, 2020 to 2025). A disease caused by infection with severe acute respiratory syndrome coronavirus 2. "The strongest positive associations in the more severe COVID-19 group, (i.e. low level when FABP2 is low) were in plasma lipids (both lipid-CH2 and lipid-CH3 regions) and lymphocytes." (PMID 36335131, 2022). "The strongest positive associations in the more severe COVID-19 group, (i.e. low level when FABP2 is low) were in plasma lipids (both lipid intramolecular CH2 and CH3 groups), and lymphocytes, both of which have been frequently observed in severe COVID-1940,43,44." (PMID 36335131, 2022). "Our results support that the COVID-19-positve patients exhibit gut barrier dysfunction as evidenced by the higher levels of FABP2, PGN, and LPS and the abnormal presence of microbes in their plasma." (PMID 36012406, 2022). "Further studies are therefore needed to confirm the relationship between plasma FABP2 levels and COVID-19 severity." (PMID 36335131, 2022). "Changes in circulating lipid levels are another feature commonly observed in severe COVID-19 and a weak positive correlation was observed in the more severe group between reduced FABP2 and reduced relative lipid-CH3 and lipid-CH2 levels." (PMID 36335131, 2022). "Relative NMR metabolite levels from 32 patients (milder COVID-19 group N = 17, more severe COVID-19 group N = 15) were compared to FABP2 and zonulin concentrations using Pearson r correlation (GraphPad Prism 9.2.0)." (PMID 36335131, 2022). "Plasma zonulin levels and FABP2 levels were measured in 17 milder COVID-19 patients and 16 more severe COVID-19 patients." (PMID 36335131, 2022). "The levels of FABP2 were higher (p = 0.0013) in the plasma of COVID-19 patients compared with healthy individuals, supporting the assertion that subjects with COVID-19 infection exhibit increased permeability of the gut barrier." (PMID 36012406, 2022). "A more extensive study of circulating markers of gut function, such as citrulline and gut cell death, is needed to confirm that the FABP2 levels in severe COVID-19 are indicative of altered lipid import and metabolism rather than apoptosis." (PMID 36335131, 2022). "Moreover, previous studies have found that in adult COVID-19 patients’ expression of plasma FABP2 is especially low in patients with the highest levels of inflammation and gut permeability." (PMID 39576310, 2024). "We propose that the reduced circulating FABP2 in moderate to severe COVID-19 is a marker of infected enterocyte functional change rather than gut damage, which could also contribute to the development of hypolipidemia in patients with more severe disease." (PMID 36335131, 2022). "Fatty acid-binding protein-2 (FABP2) levels were higher in the plasma of COVID-19 patients." (PMID 35563874, 2022). "Comparison of plasma FABP2 levels with other circulating metabolites and patient clinical data in the more severe COVID-19 group showed the strongest negative associations (i.e. high level when FABP2 is low) with CRP, Il–6 and zonulin." (PMID 36335131, 2022). "The concentration of the plasma gut permeability marker FABP2 (p = 0.0013) and the gut microbial antigens PGN (p < 0.0001) and LPS (p = 0.0049) were significantly elevated in COVID-19 patients compared to healthy subjects." (PMID 36012406, 2022). "Levels of FABP2, PGN, and LPS were significantly higher among COVID-19 patients compared to healthy subjects, suggesting translocation of pro-inflammatory antigens from a leaky gut." (PMID 34721437, 2021). "However, Intestinal Fatty Acid Binding Protein / Fatty Acid Binding Protein 2 (I-FABP/FABP2), a widely used biomarker for gut cell death, has paradoxically been shown to be reduced in moderate to severe COVID-19." (PMID 36335131, 2022). "Finally, a total of eleven differential factors related to COVID-19 disease severity were identified, including: TRAIL R1, IGFBP-1, IGFBP-4, VCAM-1, sFRP-3, FABP2, Transferrin, GDF15, IL-1F7 (also known as IL-37), IL-5Rα, and CD200." (PMID 34335566, 2021).
COVID-19 (continued). "In addition, the levels of IL-5Rα, FABP2, CD200 and transferrin consistently showed the highest levels in the moderate group, indicating that these factors may serve as sensitive biomarkers reflecting COVID-19 disease severity." (PMID 34335566, 2021).
necrotizing enterocolitis (17 papers, 2013 to 2025). Necrotizing enterocolitis (NEC) is a devastating disease that affects mostly the intestine of premature infants. "Previously, FABP-2 was identified as an early marker for diagnosing necrotizing enterocolitis in pre-term infants, being highly specific for mucosal damage in the small intestine." (PMID 37176050, 2023). "Previous studies showed the applicability of FABP2 for detection of intestinal injury after acute ischemic diseases, rejection and necrotic enterocolitis, whereas FABP2 concentrations in plasma of healthy individuals were reported to be undetectable or very low." (PMID 24278421, 2013).
depression (15 papers, 2013 to 2026). "While zonulin has yielded heterogeneous findings across depression studies, the overall trend indicates elevated levels in affected individuals, whereas serum FABP2 appears to show a more consistent increase." (PMID 41155365, 2025). "A recent study found that an elevated level of the protein fatty-acid-binding protein-2 (FABP2) in those with depression or anxiety was a sign of intestinal barrier permeability." (PMID 36678130, 2023). "Previous studies have identified that FABP2 plays a key role in the absorption and intracellular transport of dietary long-chain fatty acids, and the explanation of observed fatty acids alterations in Major Depressive Disorder." (PMID 29678171, 2018). "In addition, previous research has demonstrated that increased human intestinal barrier permeability plasma biomarkers zonulin and fatty acid binding protein-2 (FABP2) correlated with plasma lipopolysaccharide (LPS) and altered gut microbiome in anxiety and depression." (PMID 31772709, 2019).
metabolic syndrome (12 papers, 2013 to 2025). A cluster of metabolic risk factors for CARDIOVASCULAR DISEASES and TYPE 2 DIABETES MELLITUS. "As a result, both FABP1 and FABP2 are associated with diseases accompanied by dysregulated lipid levels, such as metabolic syndrome, non-alcoholic fatty liver disease, and type 2 diabetes." (PMID 37091779, 2023). "Logistic regressions of metabolic syndrome components and metabolic syndrome for rs1799883 (FABP2), rs1501299 (ADIPOQ) and rs5065 (ANP) gene polymorphisms." (PMID 27684940, 2016). "The aim of this study was to determine the associations between the mentioned gene polymorphisms (ACE, MTHFR, FABP2), and T2DM with dyslipidemia." (PMID 28890888, 2017). "The present study was aimed to investigate the association of ACE (rs4646994), FABP2 (rs1799883), MTHFR (rs1801133) and FTO (rs9939609) genes polymorphism in T2DM with dyslipidemia." (PMID 28890888, 2017). "FABP2 gene was significantly associated with T2DM without dyslipidemia compared to the controls (P<0.001)." (PMID 28890888, 2017). "In our population, FABP2 gene was significantly associated with T2DM cases without dyslipidemia compared to the controls (P<0.001)." (PMID 28890888, 2017). "In conclusion ACE, FABP2, FTO and MTHFR genes were found to be associated with T2DM, and additionally ACE and MTHFR genes might be implicated with the development of dyslipidemia in T2DM cases." (PMID 28890888, 2017). "In conclusion, the results of this study indicate that FABP2, ANP and ADIPOQ gene variants are associated with metabolic syndrome or its components in Afro-Caribbeans and suggest a cumulative effect of these variants on the risk of metabolic syndrome and hypertriglyceridemia." (PMID 27684940, 2016). "The additional risk associated with possessing several SNPs, particularly when integrating FTO, MC4R, and FABP2, increases the likelihood of developing metabolic syndrome, even in the absence of observable symptoms." (PMID 41226372, 2025). "The frequency of FABP2 AT genotype was 57.47% in T2DM cases without dyslipidemia which is significantly higher in comparison with Mexican-American (41.9%) and Saudi (38%) populations." (PMID 28890888, 2017). "We have observed that the frequency of FABP2 AA genotype was 25.3% in T2DM without dyslipidemia cases which is similar to Asians (27%), while lower in comparison with Caucasians (57%)." (PMID 28890888, 2017). "The frequency of FABP2 AA genotype was higher in T2DM with dyslipidemia cases compared to T2DM without dyslipidemia cases and the frequency of FABP2 AT genotype was significantly lower in T2DM cases with dyslipidemia compared to T2DM cases without dyslipidemia (P<0.001)." (PMID 28890888, 2017). "The frequency of FABP2 AA genotype was higher in T2DM cases with dyslipidemia compared to T2DM cases without dyslipidemia and the frequency of FABP2 AT genotype was significantly lower in T2DM cases with dyslipidemia compared to T2DM cases without dyslipidemia (P<0.001)." (PMID 28890888, 2017).
type 2 diabetes (12 papers, 2013 to 2025). "The aim of this study was to characterize the effect of this FABP2 polymorphism in Mexican-Americans with type 2 diabetes (T2D) in the context of a three-month intervention to determine if the polymorphism differentially modulates selected clinical outcomes." (PMID 26703680, 2015). "In these patients with type 2 diabetes, the presence of the Ala54Thr polymorphism of the FABP2 gene was assciated with diabetic retinopathy in Chinese." (PMID 25802555, 2015). "We previously reported an association between the Thr54 variant of FABP2 and type 2 diabetes in Mexican-Americans." (PMID 26703680, 2015). "FABP2 was linked to Type 1 Diabetes triggers, and, moreover, FABP2 gene variants may increase Type 2 Diabetes risk." (PMID 41155365, 2025). "Our findings support our hypothesis that the Ala54Thr polymorphism of FABP2 plays a distinct role in Mexican-Americans with type 2 diabetes." (PMID 26703680, 2015). "Specifically, the Ala54Thr polymorphism of FABP2 modulates HDL cholesterol in Mexican-Americans with type 2 diabetes; our results also indicate that Thr54 allele carriers may be responsive in interventions that promote changes in dietary fat intake." (PMID 26703680, 2015). "However, they did not perform the meta-analysis on the association of the FABP2 Ala54Thr polymorphism with risk of type 2 diabetes because of few studies on this association." (PMID 25388378, 2014). "Compared with control individuals, FABP2 levels were significantly increased in individuals with type 2 diabetes, with the exception of those with NPDR and no DME." (PMID 39875729, 2025). "The role of the gut–retina axis in diabetic retinopathy pathogenesis finds support in our initial study showing that the levels of peptidoglycan and fatty acid binding protein 2 (FABP2), two serum markers of gut leakage, are increased in humans with type 1 diabetes and type 2 diabetes." (PMID 39875729, 2025).
ulcerative colitis (9 papers, 2015 to 2025). An inflammatory bowel disease involving the mucosal surface of the large intestine and rectum. "FABP2 can also serve as a biomarker of intestinal inflammation, such as acute intestinal ischemia and active ulcerative colitis." (PMID 35498757, 2022).
Cirrhosis (8 papers, 2016 to 2025). A chronic disorder of the liver in which liver tissue becomes scarred and is partially replaced by regenerative nodules and fibrotic tissue resulting in loss of liver function. "Expression levels of the gut permeability marker fatty acid-binding protein 2 (FABP2) were higher in the peripheral veins of patients with cirrhosis than in those in the healthy controls." (PMID 35130114, 2022). "During cirrhosis, there is episodic bacterial translocation and persistent immune cell activation, as indicated by the increased FABP2 and CXCL13 levels in our study." (PMID 31456809, 2019). "Regarding 6-week mortality, our analysis showed that it correlated with FABP2, albumin, CRP levels, severity of liver disease, and the presence of severe cirrhosis-related complications, including portal vein thrombosis and hepatocellular carcinoma." (PMID 35308545, 2022).
psoriasis (7 papers, 2020 to 2025). An autoimmune condition characterized by red, well-delineated plaques with silvery scales that are usually on the extensor surfaces and scalp. "Moreover, it could be of value to examine the influence of antipsoriatic treatment (followed by a decrease in psoriasis severity) and body mass loss in relation to FABP-2 and intestinal-barrier integrity." (PMID 36144237, 2022). "Therefore, FABP-2 has emerged as a possible marker of psoriasis severity and its potential use should be further elucidated." (PMID 36144237, 2022). "Moreover, FABP-2 concentration positively correlated with BMI and PASI, and it was recognized as an independent predictor of psoriasis severity in patients with moderate to severe disease." (PMID 36144237, 2022).
breast carcinoma (6 papers, 2008 to 2025). "For example, breast cancer-associated fibroblasts (CAFs) promote lipid take up in tumor cells through the FABP2/FABP3 pathway, and ovarian cancer cells uptake fatty acids released by adipocytes through FABP4 to support metastasis." (PMID 40717587, 2025). "Studies have shown that breast cancer-associated fibroblasts (CAFs) promote lipid uptake in tumor cells through the FABP2/FABP3 pathway, thereby affecting tumor metabolism and growth." (PMID 40717587, 2025). "Only FABP2 and FABP3 mRNAs were found in the breast cancer cells; FABP2 expression was found to be modulated by hormones and after exposure to media conditioned by fibroblasts with increased lipid levels." (PMID 37207357, 2023). "Loss of expression of FABP4 was reported in bladder cancer while FABP1 and FABP2 are over-expressed in prostate and breast cancers." (PMID 18826602, 2008). "In vivo experiments, blocking FABP2 expression significantly inhibits tumor growth, suggesting that FABP2 may become an important target for metabolic regulation in breast cancer." (PMID 40717587, 2025). "The role of FABP2 in various cancers is increasingly attracting attention, especially in colorectal and breast cancers, and its roles in lipid metabolism, inflammatory regulation, and the tumor microenvironment may provide new ideas for therapeutic strategies." (PMID 40717587, 2025). "As a tumor biomarker: Changes in FABP2 expression in CRC, breast cancer, and gastric cancer suggest its potential as a biomarker for early cancer detection and prognosis assessment." (PMID 40717587, 2025). "NR4A1 has been found to bind to the NBRE or coactivator SWI/SNF complex response elements by NR4A2 or PPARγ, resulting in the change of fatty acid-related genes ACOX, CPT1M, FABP2, and FABP4 in melanoma and breast cancer." (PMID 36052242, 2022). "Next, we determined the correlation between increased CD36 expression and the various FABP genes (FABP1, FABP2, FABP3, FABP4, FABP5 and FABP6) in the TCGA breast cancer cohort." (PMID 34561446, 2021). "As a therapeutic target: Inhibiting FABP2-mediated lipid metabolism pathways may provide new therapeutic strategies for CRC and breast cancer." (PMID 40717587, 2025). "Moreover, as found for FABP2, FABP3 mRNA was discovered in breast cancer culture cells where its expression is modulated by hormones and after exposure to media conditioned by fibroblasts." (PMID 37207357, 2023).
colitis (6 papers, 2013 to 2025). Inflammation of the colon. "After colitis onset, treatment with MSPNPs was more effective than that with free MSPs in restoring the expressions of tight-junction-related genes (upregulation of occludin, ZO-1, JAM, MUC and FABP-2) and beneficial gut microbiota." (PMID 35745756, 2022).
colorectal cancer (6 papers, 2013 to 2025). A primary or metastatic malignant neoplasm that affects the colon or rectum. "Our analysis revealed an association between rs1799883 in the FABP2 gene and colorectal cancer (CRC), with cases exhibiting a higher frequency of the homozygous dominant (GG) genotype, while controls had a higher frequency of the heterozygous (GA) genotype." (PMID 39242607, 2024). "FABP2 gene polymorphisms and colorectal cancer susceptibility: Multiple studies have shown that single nucleotide polymorphisms (SNPs) in the FABP2 gene may affect the incidence of CRC." (PMID 40717587, 2025). "The role of FABP2 in the colorectal cancer microenvironment: Studies have found that FABP2 expression is regulated by the Wnt/β-catenin/PPARγ signaling pathway, which plays an important role in intestinal cell differentiation and carcinogenesis." (PMID 40717587, 2025). "The role of FABP2 in colorectal cancer stem cells and differentiation: In colorectal cancer stem cell research, FABP2 has been found to co-regulate with intestinal epithelial differentiation markers (such as KLF4, CA1)." (PMID 40717587, 2025). "Additionally, FABP2 shows low response to BMP4 signaling in intestinal organoid cultures, suggesting its potential impact on the differentiation capacity of colorectal cancer cells." (PMID 40717587, 2025).
Hypertension (6 papers, 2007 to 2023). The presence of chronic increased pressure in the systemic arterial system. "The FABP2 (rs1511025)/FABP2 (rs1799883) interaction was recovered in some subpopulations, but all with very low WMI and none significantly influenced the prevalence of hypertension." (PMID 25788903, 2015).
hypertriglyceridemia (6 papers, 2012 to 2024). A laboratory test result indicating elevated triglyceride concentration in the blood. "Studies have shown that the FABP2 Ala54Thr polymorphism is significantly associated with postprandial hypertriglyceridemia." (PMID 37537524, 2023). "Our results show a significant association between the presence of the Ala54Thr FABP2 gene polymorphism and postprandial hypertriglyceridemia." (PMID 30217061, 2018). "The presence of the Ala54Thr polymorphism of the FABP2 gene appears to be involved in postprandial hypertriglyceridemia." (PMID 30217061, 2018). "FABP2 Ala54Thr polymorphism (rs1799883) was significantly associated with hypertriglyceridemia (OR = 2.22; P = 0.014)." (PMID 27684940, 2016). "Our results suggest that the Ala54Thr polymorphism (rs1799883) of the FABP2 gene may be one of the genetic factors that contribute to the development of postprandial hypertriglyceridemia." (PMID 30217061, 2018). "Twenty three FABP2 Ala54 and twenty three Thr54 carriers with hypertriglyceridemia were enrolled in this study." (PMID 23497599, 2012).
Stroke (6 papers, 2007 to 2023). Sudden impairment of blood flow to a part of the brain due to occlusion or rupture of an artery to the brain. "After using multivariable logistic recessive adjusted risk factors for IS, we found that patients with the FABP2 rs1799883 GA genotype had a significantly higher risk of stroke in the codominant inheritance model (adjusted odds ratio (OR):3.431; 95%Confidence interval (CI):1.060–11.103; p = 0.04)." (PMID 37091779, 2023). "Several genes involved in lipid metabolism such as Paraoxonase (PON), Lipoprotein Lipase (LPL) and Fatty Acid-Binding Protein 2 (FABP2) have been examined in the stroke populations." (PMID 17553166, 2007).